PCDHA4 (protocadherin alpha 4)
Description:
Calcium-dependent cell-adhesion protein involved in cells self-recognition and non-self discrimination. Thereby, it is involved in the establishment and maintenance of specific neuronal connections in the brain.
Synonyms: CNR1; CRNR1; PCDH-ALPHA4; CNRN1
Tractability: Antibody: its Gene Ontology location is reachable by antibodies, with high confidence; UniProt places it where antibodies can reach, with medium confidence; UniProt predicts a signal peptide or a membrane-spanning region; the Human Protein Atlas places it where antibodies can reach.
Gene: Protein-coding gene on chromosome 5 (140,807,037 to 141,012,347, forward strand). Ensembl gene ENSG00000204967.
Subcellular location: Cell membrane
Subcellular location (Human Protein Atlas): Nucleoplasm; Plasma membrane; Cytosol
Gene Ontology:
Molecular function: protein binding; calcium ion binding; cell adhesion molecule binding; identical protein binding
Biological process: cell adhesion; nervous system development; homophilic cell-cell adhesion
Cellular component: plasma membrane; membrane
Genetic constraint (gnomAD): Loss-of-function variants: 49 observed, 63.67 expected, observed/expected ratio (o/e) 0.77, 90% interval 0.61 to 0.98. The upper end of that interval is the gene's LOEUF score, 0.98, which puts it in group 4 of 6, group 1 being the genes least tolerant of losing a copy. Missense variants: 1,253 observed, 1,295 expected, observed/expected ratio (o/e) 0.97, 90% interval 0.92 to 1.01. Synonymous variants: 590 observed, 569.4 expected, observed/expected ratio (o/e) 1.04, 90% interval 0.97 to 1.11.
Homologues: Orthologues: mouse Pcdha4 (86% identical), mouse Pcdha10 (81% identical). Paralogues in human: PCDHA7 (85% identical), PCDHA3 (85% identical), PCDHA9 (84% identical), PCDHA13 (83% identical), PCDHA2 (83% identical), PCDHA5 (82% identical), PCDHA1 (81% identical), PCDHA6 (81% identical), PCDHA10 (81% identical), PCDHA8 (81% identical), PCDHA11 (81% identical), PCDHA12 (80% identical), and 49 more.
Diseases named in the same sentence as PCDHA4 in open-access papers:
PCDHA4 is named in the same sentence as 10 diseases in open-access papers, as found by Europe PMC text mining. Sharing a sentence is not in itself a finding about the gene and the disease. The quoted sentences say what the papers report.
cervical cancer (2 papers, 2015 to 2023). A primary or metastatic malignant neoplasm involving the cervix. "Comparing to high-risk HPV test, methylated PCDHA4 and PCDHA13 were as frequently found in invasive cervical cancer but was much less frequently found in normal or CIN1." (PMID 25418975, 2015).
breast carcinoma (1 paper, 2022). "As an example of TET2 CD–mediated gene activation, a subset of TSS-CGIs from the breast cancer-methylated PDCHA locus selectively gained H3K4me3 in TET2 CD cells in correlation with the activation of the associated genes as shown for PCDHA4, PCDHA3, PCDHA9, and PCDHA10." (PMID 35351824, 2022). "Interrogation of TCGA RNA-seq data from breast cancer samples supported the data obtained from MCF-7 cells, showing that PCDHA4 expression levels are positively correlated with TET2 expression in patients." (PMID 35351824, 2022).
metastatic tumor (1 paper, 2016). "Preliminary functional studies also suggested that PCDHA4 could play a tumor suppressor role since it was hypermethylated and silenced in alveolar RMS cell lines representative of a metastatic tumor." (PMID 27842508, 2016).
rhabdomyosarcoma (1 paper, 2016). A rare aggressive malignant mesenchymal neoplasm arising from skeletal muscle. "Further functional studies are warranted to clarify the involvement of PCDHA4 in rhabdomyosarcoma." (PMID 27842508, 2016).
cancer (3 papers, 2015 to 2023). A tumor composed of atypical neoplastic, often pleomorphic cells that invade other tissues. "The study also reported that there was a positive correlation between methylation frequency of PCDHA4 and PCDHA13 and tumor severity, highlighting the role of PCDHA4 silencing in cancer progression." (PMID 27842508, 2016).
tumor (3 papers, 2014 to 2023). "Among them, three (NAMPT, PCDHA4, and AXL) have been reported to be associated with the pathogenesis of this tumor." (PMID 36918772, 2023). "Three of thirty-nine proteins (PCDHA4, AXL, and NAMPT) correlate with RMS and RMS-associated tumor behavior." (PMID 36918772, 2023). "To evaluate the potential role of PCDHA4 as a tumor suppressor in RMS, we transiently silenced PCDHA4 in RH36, which is the ERMS cell line with the highest endogenous expression level of this gene." (PMID 27842508, 2016). "As PCDHA4-silenced cells have a significantly higher cell proliferation rate paralleled by higher cell invasiveness, PCDHA4 seems to behave as a tumor suppressor in metastatic RMS." (PMID 27842508, 2016). "These preliminary data uncovered the potential role of PCDHA4 as a tumor suppressor in RMS." (PMID 27842508, 2016). "Taken together these preliminary results suggest that PCDHA4 could play the role of a tumor suppressor and may be involved in promoting cell cycle progression and cell invasion of RMS cells." (PMID 27842508, 2016). "Preliminary data also suggested that PCDHA4 may act as a tumor suppressor in RMS cells and that it may be partially inactivated by DNA methylation." (PMID 27842508, 2016).
PCDHA4 also shares sentences with these, for which no sentence is quoted: Alzheimer disease (1 paper); parasite infections (1); Parkinson disease (1); schizophrenia (1).